FGR (FGR proto-oncogene, Src family tyrosine kinase)
Description:
Non-receptor tyrosine-protein kinase that transmits signals from cell surface receptors devoid of kinase activity and contributes to the regulation of immune responses, including neutrophil, monocyte, macrophage and mast cell functions, cytoskeleton remodeling in response to extracellular stimuli, phagocytosis, cell adhesion and migration. Promotes mast cell degranulation, release of inflammatory cytokines and IgE-mediated anaphylaxis. Acts downstream of receptors that bind the Fc region of immunoglobulins, such as MS4A2/FCER1B, FCGR2A and/or FCGR2B. Acts downstream of ITGB1 and ITGB2, and regulates actin cytoskeleton reorganization, cell spreading and adhesion. Depending on the context, activates or inhibits cellular responses. Functions as a negative regulator of ITGB2 signaling, phagocytosis and SYK activity in monocytes. Required for normal ITGB1 and ITGB2 signaling, normal cell spreading and adhesion in neutrophils and macrophages. Functions as a positive regulator of cell migration and regulates cytoskeleton reorganization via RAC1 activation. Phosphorylates SYK (in vitro) and promotes SYK-dependent activation of AKT1 and MAP kinase signaling. Phosphorylates PLD2 in antigen-stimulated mast cells, leading to PLD2 activation and the production of the signaling molecules lysophosphatidic acid and diacylglycerol. Promotes activation of PIK3R1. Phosphorylates FASLG, and thereby regulates its ubiquitination and subsequent internalization. Phosphorylates ABL1. Promotes phosphorylation of CBL, CTTN, PIK3R1, PTK2/FAK1, PTK2B/PYK2 and VAV2. Phosphorylates HCLS1 that has already been phosphorylated by SYK, but not unphosphorylated HCLS1. Together with CLNK, it acts as a negative regulator of natural killer cell-activating receptors and inhibits interferon-gamma production (By similarity).
Synonyms: SRC2; c-fgr; p55c-fgr; c-src2; p55-Fgr; p58-Fgr; p58c-fgr
Tractability: Small molecule: an approved drug acts on it; a structure with a bound ligand is known; a high-quality ligand is known; it belongs to a druggable protein family. Antibody: UniProt places it where antibodies can reach, with high confidence; its Gene Ontology location is reachable by antibodies, with high confidence; the Human Protein Atlas places it where antibodies can reach. PROTAC: UniProt records ubiquitination sites on it; ubiquitination databases record sites on it; its protein half-life has been measured; a small molecule that binds it is known.
Target class: Kinase; TK protein kinase group; Enzyme; Protein Kinase; Tyrosine protein kinase Src family
Gene: Protein-coding gene on chromosome 1 (27,612,064 to 27,635,565, reverse strand). Ensembl gene ENSG00000000938.
Subcellular location: Cell membrane; Cell projection, ruffle membrane; Cytoplasm, cytosol; Cytoplasm, cytoskeleton; Mitochondrion inner membrane; Mitochondrion intermembrane space
Subcellular location (Human Protein Atlas): Plasma membrane; Aggresome
Pathways (Reactome):
Disease: FCGR3A-mediated IL10 synthesis; FCGR3A-mediated phagocytosis
Immune System: FCGR activation; Neutrophil degranulation
Hemostasis: Platelet sensitization by LDL
Gene Ontology:
Molecular function: Fc-gamma receptor I complex binding; non-membrane spanning protein tyrosine kinase activity; phosphotyrosine residue binding; protein binding; protein tyrosine kinase activity; immunoglobulin receptor binding; protein kinase binding; signaling receptor binding; ATP binding; protein kinase activity
Biological process: integrin-mediated signaling pathway; peptidyl-tyrosine phosphorylation; positive regulation of phosphatidylinositol 3-kinase/protein kinase B signal transduction; protein autophosphorylation; cell differentiation; cell surface receptor protein tyrosine kinase signaling pathway; defense response to Gram-positive bacterium; Fc-gamma receptor signaling pathway involved in phagocytosis; immune response-regulating cell surface receptor signaling pathway; negative regulation of inflammatory response to antigenic stimulus; positive regulation of cell migration; positive regulation of cytokine production; positive regulation of mast cell degranulation; protein phosphorylation; regulation of cell shape; regulation of innate immune response; regulation of phagocytosis; regulation of protein kinase activity; response to virus; negative regulation of natural killer cell activation
Cellular component: cytoskeleton; extracellular exosome; actin cytoskeleton; cytosol; extracellular region; plasma membrane; ruffle membrane; secretory granule lumen; mitochondrial inner membrane; mitochondrial intermembrane space
Genetic constraint (gnomAD): Loss-of-function variants: 25 observed, 62.81 expected, observed/expected ratio (o/e) 0.4, 90% interval 0.29 to 0.56. The upper end of that interval is the gene's LOEUF score, 0.56, which puts it in group 2 of 6, group 1 being the genes least tolerant of losing a copy. Missense variants: 508 observed, 703.92 expected, observed/expected ratio (o/e) 0.72, 90% interval 0.67 to 0.78. Synonymous variants: 286 observed, 285.33 expected, observed/expected ratio (o/e) 1, 90% interval 0.91 to 1.11.
Homologues: Orthologues: chimpanzee FGR (99% identical), macaque FGR (98% identical), pig FGR (91% identical), dog FGR (90% identical), guinea pig FGR (89% identical), rabbit FGR (89% identical), rat Fgr (85% identical), mouse Fgr (84% identical), tropical clawed frog fgr (72% identical), zebrafish yrk (71% identical). Paralogues in human: FYN (72% identical), YES1 (69% identical), SRC (67% identical), HCK (55% identical), LYN (54% identical), BLK (52% identical), LCK (51% identical), FRK (47% identical), ABL2 (40% identical), ABL1 (39% identical), SRMS (38% identical), PTK6 (37% identical), and 20 more.